HMGB1 (high mobility group box 1)
Diseases named in the same sentence as HMGB1 in open-access papers (continued):
Sharing a sentence is not in itself a finding about the gene and the disease.
colitis (57 papers, 2009 to 2026). Inflammation of the colon. "Consistent with previous findings, higher levels of HMGB1 were observed in DSS-induced colitis models in mice concomitant with weight loss, shortened colon length, elevated DAI scores, and aggravation of pathologic damage." (PMID 40689397, 2025). "Nevertheless, the anti-inflammatory effect of VNS proved to be effective even in such a severe model of colitis resulting in a significant improvement of survival compared to sham-treated mice, a finding associated with a reduction in HMGB1 serum levels." (PMID 29791477, 2018). "Ample evidence indicates that HMGB1 is an important mediator in the pathogenesis of colitis and colitis associated carcinoma." (PMID 25127031, 2014). "Thus, in the DSS colitis carcinogenesis model, an increase in HMGB1 was associated with decreased epithelial differentiation, impaired intestinal flora, a decrease in activated CD8+ and naïve CD8+ cells, and an increase in exhausted CD8+ and Treg cells." (PMID 38999957, 2024). "In studies of colitis, HMGB1 release was associated with a pro-inflammatory role." (PMID 36551259, 2022). "Similarly, HMGB1 has been shown to mediate colitis-associated tumors, which can be decreased in incidence and size by anti-HMGB1 antibody treatment." (PMID 26486085, 2015). "Neutralizing HMGB1 activity by administration of anti-HMGB1 antibodies or ethyl pyruvate attenuates colon injury, reduces weight loss and improves colon scores in animal models of colitis." (PMID 25127031, 2014). "Because HMGB1 is over-expressed in GC, blocking of HMGB1 production or release, or preventing its interaction with its receptor(s) might provide an important opportunity for the prevention or treatment of GC as shown in a colitis-associated cancer model." (PMID 19476625, 2009). "Co-targeting HMGB1 alongside DNase I enhances therapeutic benefit in murine colitis, yielding greater reductions in inflammation than either intervention alone." (PMID 40806230, 2025). "Its expression is markedly elevated in inflamed UC mucosa, and neutralization of HMGB1 in DSS-induced colitis models alleviates barrier dysfunction and intestinal inflammation by regulating NET formation and macrophage polarization." (PMID 40806230, 2025). "In the DSS-induced colitis model, HMGB1 overexpression was accompanied by downregulation of the barrier proteins Occludin, E-cadherin, and Claudin-1, which was reversed by DPG intervention, as further corroborated by immunofluorescence staining results." (PMID 40689397, 2025). "Last, inhibition of HMGB1 ameliorated intestinal inflammation in a mouse model of colitis, however, how to target HMGB1 safely and effectively in the clinic still requires further investigation." (PMID 40689397, 2025). "The TLR4/NFκB pathway also plays a crucial role in colitis pathogenesis and interacts with the HMGB1/RAGE axis to further amplify the inflammatory response." (PMID 40606616, 2025). "Mechanistically, ALG-RSV-CSNPs effectively attenuated colitis by significantly inhibiting the HMGB1-triggered RAGE/TLR4-NFκB inflammatory signaling pathway." (PMID 40606616, 2025). "HMGB1-activated RAGE/TLR4-NFκB signaling is a key regulator of inflammatory responses in DSS-induced colitis." (PMID 40606616, 2025). "In a DSS-induced colitis model, inhibition of HMGB1 was observed to increase intestinal Occludin, E-cadherin, and Claudin-1 expression in experimental mice." (PMID 40689397, 2025). "Next, we investigated the role of HMGB1 in colitis carcinogenesis using a mouse model of DSS colitis combined with AOM." (PMID 38999957, 2024). "VNS significantly improved survival, reduced serum HMGB1 levels, and attenuated systemic inflammatory responses in a Th2-driven colitis model." (PMID 39605787, 2024). "We found that PARP1−/− mice show less severe colitis highlighted by improved clinical parameters as well as by significantly reduced amounts of serum and fecal HMGB1." (PMID 37108260, 2023).
colitis (continued). "In sum, after treatment with DSS, PARP1−/− mice show less severe colitis compared to wild type mice, as evidenced by the significantly reduced amounts of serum and fecal HMGB1." (PMID 37108260, 2023). "Accordingly, we showed that HMGB1 is highly expressed in the inflamed intestinal tissues of CD and UC patients and that experimental colitis in mice is highly improved by inhibiting HMGB1." (PMID 37108260, 2023). "Results show that PARP1−/− mice develop less severe colitis than WT mice, evidenced by a significant decrease in fecal and serum HMGB1, and, similarly, treating WT mice with PJ34 reduces the secreted HMGB1." (PMID 37108260, 2023). "Ethyl pyruvate, a redox analog of DMF, exerted similarly beneficial effects in a murine model of colitis, leading to the improvement of symptoms and a decrease in high mobility group box 1 (HMGB1), a key mediator of inflammation." (PMID 37373057, 2023). "In TNBS-induced colitis and IL-10−/− mice, administration of ethyl pyruvate attenuated colitis and reduced HMGB1 expression." (PMID 36551259, 2022). "In a mouse model of DSS-induced colitis, Gsdme-knockout mice exhibited reduced inflammation, and Gsdme−/− mice release higher levels of high mobility group box 1 (HMGB1) from IECs." (PMID 35677444, 2022). "Notwithstanding, therapeutic avenues to modulate HMGB1 signalling warrant exploration as adjunct treatments for colitis to suppress the neuroinflammatory component." (PMID 36551259, 2022). "GSDME deficiency effectively reduces HMGB1 release from colonic tissues, alleviating inflammation in a mouse model of DSS-induced colitis." (PMID 35677444, 2022). "The mRNA expressions of NLRP3, ASC, caspase-1, GSDMD, IL-18, and HMGB1 were shown to increase in different extents in colitis tissues than in control tissues, whereas SM934 treatment decreased the expression of these genes." (PMID 36120344, 2022). "In DNBS-induced colitis, increased expression of the HMGB1 gene in the hippocampus has been suggested to be detrimental to hippocampal neurogenesis and function." (PMID 34983592, 2022). "Studies in chemically-induced colitis by dextran sodium sulphate (DSS) have demonstrated that inhibition of HMGB1 can be effective as a preventative treatment against intestinal inflammation." (PMID 36551259, 2022). "In animal models of colitis, increased HMGB1 expression in colon tissues has been observed in mouse models of 2,4,6-trinitrobenzenesulfonic acid (TNBS), DSS chemically-induced colitis and interleukin (IL)-10 deficient mice." (PMID 36551259, 2022). "In an animal model of colitis, the expression of HMGB-1 increased in the intestinal tissue, and compared with those infants without NEC, the fecal level of HMGB-1 of those with NEC was significantly higher." (PMID 36582510, 2022). "It was also found that melatonin can improve DSS-induced colitis through the suppression of HMGB1 in intestinal tissues." (PMID 34418984, 2021). "In intestinal diseases, it was found that HMGB1 can promote experimental colitis in a mouse model through the regulation of IL-23." (PMID 34418984, 2021). "Western blotting showed that HMGB1 expression in both the nucleus and cytoplasm were down-regulated after the administration of HnAb as compared to IgY-treated colitis mice." (PMID 33193406, 2020). "Because toll-like receptor 4 (TLR4) is implicated in HMGB1-mediated immune cell activation, DSS colitis was also elicited in TLR4-deficient mice in the presence and absence of HnAb." (PMID 33193406, 2020). "Nonetheless, nuclear and cytoplasmic HMGB1 was elevated in colonic tissues in DSS-colitis mice compared to the normal control mice." (PMID 33193406, 2020). "HMGB1 is suggested as a potential biomarker in IBD patients’ feces, while anti-HMGB-1 therapy seems to be promising in a mouse model of colitis." (PMID 32516975, 2020). "In recent years, the protective effect of HMGB1 inhibition on colitis has gradually attracted an attention." (PMID 33193406, 2020).
colitis (continued). "HnAb was administrated into mice with DSS-induced colitis to investigate the effect of HMGB1 inhibition on colitis severity." (PMID 33193406, 2020). "HMGB1 is a well-known DNA-binding protein, which offers an opportunity to sequester HMGB1 via DNA-conjugated beads that has been studied in experimental colitis." (PMID 32265930, 2020). "To further confirm the impact of HMGB1 on Treg function in vivo, we used the well-established T cell-transfer model of colitis in NOD-scid mice." (PMID 32072192, 2020). "The purpose of this study was to investigate the protective effect of anti-HMGB1 neutralizing-antibody (HnAb) in dextran sulfate sodium (DSS)-induced colitis." (PMID 33193406, 2020). "Semiquantitative IHC suggested that HMGB1 expression was inhibited significantly in colonic tissues of HnAb-treated mice as compared to vehicle-treated mice with DSS-induced colitis." (PMID 33193406, 2020). "The protective effect of this antibody was enhanced in TLR4-deficient mice in some aspects, indicating that both additional HMGB1-mediated as well as TLR4-mediated inflammatory signaling pathways were involved in the induction of colitis by DSS." (PMID 33193406, 2020). "A previous study demonstrated that HMGB1 plays essential roles in the development of DSS-induced colitis." (PMID 33160389, 2020). "Evidence indicates that n-3 PUFAs and n-9 PUFAs, respectively, upregulate the TLR-2 and TLR-4 genes of TNBS-induced colitis, while n-6 PUFAs influence high-mobility group box 1 (HMGB1), a reactivator of TLR gene." (PMID 31780872, 2019). "In summary, here we describe a novel approach using HMGB1-specific DNA beads to effectively sequester HMGB1, and improve disease pathogenesis in clinically relevant models of colitis." (PMID 25127031, 2014). "Analysis of the focal concentration of HMGB1 in the colon have demonstrated that HMGB1 is released by colonic tissue in animal models of colitis." (PMID 25127031, 2014). "Taken together, these observations demonstrate that HMGB1 levels are elevated locally in the colonic micro-environment, and DNA beads can be utilized to sequester and reduce HMGB1 levels from colitis colon." (PMID 25127031, 2014). "In IBD patients and mice with colitis, HMGB1 is secreted by inflamed intestinal tissues and present at high levels in the feces." (PMID 25127031, 2014). "As expected, HMGB1 captured by B1 or B2 beads from feces of colitis mice contained a mixture of pro-inflammatory isoforms (cytokine-inducing disulfide HMGB1 and fully reduced HMGB1)." (PMID 25127031, 2014). "Neutralizing HMGB1 activity by administration of anti-HMGB1 antibodies or HMGB1-specific antagonist improves clinical outcomes in animal models of colitis." (PMID 25127031, 2014). "Taken together, B1 and B2 beads can sequester different redox and acetylated forms of HMGB1 found in the fecal environment of colitis animals." (PMID 25127031, 2014). "HMGB1 from colitis feces and captured by DNA beads was hyper-acetylated in both nuclear localization sequences (NLS1 and NLS2)." (PMID 25127031, 2014). "To this end, we have analyzed the redox status of HMGB1 sequestered from colitis fecal material using DNA beads." (PMID 25127031, 2014). "Together, these findings establish that the DNA beads can selectively sequester HMGB1 from colitis colons and improve disease pathophysiology in experimental models of colitis." (PMID 25127031, 2014). "In the present study we investigated the presence of HMGB1 in the stools of control mice or mice with a DSS-induced colitis and found that, like in humans, the protein is strongly expressed in mice with colitis (p<0.001), but not in controls." (PMID 23840500, 2013). "In a DSS-induced colitis model, we observed that activation of the HMGB1/TLR4/NF-kB pathway resulted in decreased GPX4 expression, accompanied by increased mRNA levels of ferroptosis-related indicators (PTGS2, IREB2, CS, RPL8, and ATP5G3), which was further verified by cellular experiments." (PMID 40689397, 2025).
colitis (continued). "Importantly, inhibition of HMGB1 ameliorated body weight loss, shortened colon length, DAI scores, and histopathological damage in DSS-induced colitis mice." (PMID 40689397, 2025). "To verify whether HMGB1 mediated intestinal barrier damage is associated with ferroptosis, we conducted a systematic study in a DSS-induced colitis model." (PMID 40689397, 2025). "Our data showed that lymphocyte alterations in colitis carcinogenesis paralleled HMGB1 levels, which may play an important role in this process." (PMID 38999957, 2024). "Furthermore, G suppressed the proliferation of Th17 cells in colitis and inhibited the ability of dendritic cells and macrophages to induce the differentiation of Th17 cells that was enhanced in the presence of HMGB1." (PMID 35456938, 2022). "Likewise, high levels of HMGB1 are observed in animal models of experimental colitis and inflammatory bowel disease (IBD) patients." (PMID 36551259, 2022). "In DSS-induced colitis, the efficacy of direct HMGB1 inhibitors has been evaluated." (PMID 36551259, 2022). "HMGB1 expression could play a critical role in synaptic dysfunction and/or impaired neurogenesis in colitis models." (PMID 34983592, 2022). "Daily treatment with dipotassium glycyrrhizate reduced HMGB1 release and attenuated colitis." (PMID 36551259, 2022). "In addition, we examined the expression of the inflammatory mediator HMGB1 in TNBS-induced rat colitis." (PMID 34884536, 2021). "Reducing HMGB1 level by probiotic supplementation in mice could partially ameliorate 2,4,6-trinitrobenzenesulfonic acid-induced murine colitis." (PMID 33193406, 2020). "In order to evaluate whether HMGB1 was translocated from nucleus to cytoplasm and extracellular region in colitis, IHC, and Western blotting were performed." (PMID 33193406, 2020). "The findings indicated that, in the course of colitis, HMGB1 was transported from nucleus to cytoplasm and even extracellular region, and HnAb could hamper the redistribution of nuclear HMGB1 into cytoplasm." (PMID 33193406, 2020). "HMGB1 was found to aggravate colonic inflammation by activating the immune response in colitis." (PMID 33193406, 2020). "It suggested that strategies against HMGB1 might provide a potential interventional approach for the treatment of colitis." (PMID 33193406, 2020). "Conversely, HMGB1 was over-expressed in the GS samples treated with 25 μg of A. caninum ES, suggesting that high levels of ES counter the anti-inflammatory effects of the lower dosages, making it unsuitable for the treatment of colitis in this model." (PMID 28191818, 2017). "The necrotic cells arising from dextran sulfate sodium-induced colitis may account for the high levels of HMGB1." (PMID 26486085, 2015). "HMGB1 levels are increased in inflamed colons and in feces with both human and murine colitis." (PMID 25127031, 2014). "An interesting question is whether any specific redox isoform of HMGB1 is predominantly present during active phase of colitis." (PMID 25127031, 2014). "In our study, we aimed at assessing the usefulness of glycyrrhizin for the treatment of murine experimentally-induced colitis by examining a wider range of molecular and morphological end-points and highlighting the close relation between glycyrrhizin efficacy and HMGB1 reduced activity." (PMID 23840500, 2013). "Finally, we observed that HMGB1 is present in a significant amount in the stools of mice with colitis as compared to controls, where it is almost undetectable." (PMID 23840500, 2013). "In addition to these reports, recent evidence demonstrated that mice with chemically induced colitis exhibited elevated levels of serum HMGB1, and antibody-mediated neutralization of serum HMGB1 decreased the frequency of cancer formation." (PMID 22496788, 2012).
colitis (continued). "Additionally, recent evidence suggests that hydrogen sulfide (H2S) donors may exert protective effects by inhibiting PAD4, Cit-H3, and MPO expression, and by suppressing NF-κB and HMGB1 signaling pathways in TNBS-induced colitis models." (PMID 40806230, 2025). "Furthermore, HMGB1 inhibition ameliorates colitis in animal models." (PMID 38999957, 2024). "Further investigation suggests that the neuroprotective properties of MSC treatments in colitis could prevent necrotic-like cell death by targeting cytokines such as high mobility group box 1 protein (HMGB1) whose levels are elevated in the faeces of colitis patients." (PMID 38503815, 2024). "Overall, pro-inflammatory cytokines, HMGB1, glial cells and, synaptic dysfunction could independently or in unison be responsible for alterations in neurobiological pathways which promote suppression of neurogenesis seen in colitis." (PMID 34983592, 2022). "In line with this assertion, increased CSF levels of high mobility group box protein 1 (HMGB1), a damage-associated molecular pattern molecule (DAMP) that we identified as predictive of poor outcomes in TBI patients, enhanced colonic ILC3 to exacerbate colitis." (PMID 33427206, 2021). "TLR4 receptor might be one of the major receptors for HMGB1 in DSS-induced colitis." (PMID 33193406, 2020). "We show that dipotassium glycyrrhizate (DPG), a salt of glycyrrhizin, impairs HMGB1 activity and its administration causes a decreased loss of body weight and large intestine length as well as an amelioration in clinical and histological scores in mice with DSS-induced colitis." (PMID 23840500, 2013). "Post-colitis (therapeutic) EP administration produced greater suppression of MMP-2, MMP-9, NF-κB, HMGB1 and iNOS, along with superior restoration of TAC (P < 0.05), indicating timing-dependent modulation of inflammatory and matrix degradation pathways." (PMID 42307112, 2026). "In this study, we observed HMGB1 expression significant upregulation in patients with UC and DSS-induced colitis models in mice." (PMID 40689397, 2025). "Therefore, our study established DSS-induced colitis models and Caco-2 monolayer cell models to test our hypothesis, reveal the molecular mechanism of HMGB1-induced ferroptosis and intestinal barrier damage, provide potential therapeutic targets for UC treatment." (PMID 40689397, 2025). "In our experiments, WT mice, cotreated with DSS to induce an acute colitis and PJ34 showed a significant decrease in fecal HMGB1." (PMID 37108260, 2023). "It was also reported that luteolin reduced the expression level of the HMGB1/NF-κB signal axis in the intestinal tracts of mice, thereby alleviating dextran sodium sulfate (DSS)- incited colitis." (PMID 36611692, 2022). "The role of HMGB1 in inflammation has been illuminated in various studies, including NEC and experimental colitis." (PMID 34418984, 2021). "Together, these data support the idea that VNS attenuates HMGB1 levels and affects the colonic immune response, mainly reducing IL-6 and CXCL1 production in oxazolone-induced colitis eventually leading to an improved survival." (PMID 29791477, 2018). "Sulfz also abated the inflammatory mediators HMGB1, TNF-α and consequently RAGE, as compared to the colitis group." (PMID 29572553, 2018). "Together these studies suggest that HMGB1 is an important target in IBD, and sequestration and or neutralization of HMGB1 would be beneficial for controlling the disease severity in colitis." (PMID 25127031, 2014). "These DNA beads bind HMGB1 with high affinity, capture HMGB1 ex vivo from activated RAW 264.7 cell supernatants and from feces of colitis mice." (PMID 25127031, 2014). "Elevated levels of HMGB1 have been detected in inflamed human intestinal tissues and in feces of IBD patients and mouse models of colitis." (PMID 25127031, 2014).